EGFR (epidermal growth factor receptor)
Diseases named in the same sentence as EGFR in open-access papers (continued):
Sharing a sentence is not in itself a finding about the gene and the disease.
pancreatic cancer (continued). "The ability to characterise CTCs downstream of ISET filtration in a flexible manner may facilitate measurement of predictive biomarkers allowing stratification of pancreatic cancer patients most likely to benefit from novel targeted therapies, for example, KRAS and EGFR mutation analysis." (PMID 22187035, 2012). "In addition, because matuzumab is an IgG1 antibody to the EGFR able to mediate antibody-dependent cellular cytotoxicity, additional cytotoxic mechanisms may be involved in its effects in pancreatic cancer." (PMID 16622465, 2006). "As a recent phase II study indicates, that EGFR-targeted therapy in combination with gemcitabine might improve the outcome in pancreatic cancer, we initiated an experimental course of gemcitabine in combination with EGFR antibody (cetuximab) for a patient suffering from unresectable CC." (PMID 16846514, 2006). "CA19-9 itself can bind to the extracellular matrix, activate the epidermal growth factor receptor (EGFR) signaling pathway, and interact with the KrasG12D oncogene to promote pancreatic cancer growth." (PMID 41361823, 2025). "The liposomal nanocarrier was tested with human pancreatic cancer cell lines that express EGFR, and the EGF-decorated liposome enhanced the antitumor activity of curcumin in pancreatic cancer chemotherapy." (PMID 39891180, 2025). "In the present study, we evaluated the expression of CDH1, VIM, EGFR, ERK1, ERK2, c-Jun, and c-Fos in 24 paired healthy and tumor tissues from pancreatic cancer patients who underwent resection surgery." (PMID 40305202, 2025). "Erlotinib is an epidermal growth factor receptor (EGFR) tyrosine kinase inhibitor that has been approved for use in NSCLC in 2004 and pancreatic cancer in 2005." (PMID 41041647, 2025). "High glucose levels can stimulate the epidermal growth factor receptor (EGFR) and activate the RAS signaling pathway in some cancer cells, such as pancreatic tumor cells." (PMID 41465460, 2025). "In the present study, the gene expression of key players in EMT—CDH1 and VIM—and the MAPK/ERK pathway—EGFR, ERK1, ERK2, c-Jun, and c-Fos—was assessed in paired healthy and neoplastic tissues of the same pancreatic cancer cohort." (PMID 40305202, 2025). "The level of EGFR protein was markedly lower after incubation with C60BUT (45 μM) and C70BUT-ERL in mouse pancreatic cancer." (PMID 39916650, 2025). "In pancreatic tumor tissues, CDH1 was correlated with EGFR (r = 0.744, p < 0.05) and ERK1 (r = 0.689, p < 0.05)." (PMID 40305202, 2025). "To validate these findings in vivo, we established an orthotopic allograft tumor model by co‐injecting murine pancreatic cancer cells with up‐regulated PPY expression and KPC CAFs with decreased EGFR expression." (PMID 40162859, 2025). "The relative gene expression of EGFR, ERK1, ERK 2, c-Jun, and c-Fos was also evaluated according to the aggressiveness and invasiveness grade of the pancreatic tumors." (PMID 40305202, 2025). "Compound 17 (quercetin-3-methyl ether) interacted with multiple key targets related to pancreatic cancer, including AKT1, EGFR, TNF, CASP3, and SRC, and occupies a central position within the PPI network, indicating the potential regulatory interaction." (PMID 41006588, 2025). "Reports revealed that CD133 physically and functionally interacts with EGFR, facilitating AKT pathway activation in hepatocellular carcinoma and pancreatic cancer." (PMID 41451369, 2025). "In lung adenocarcinoma and pancreatic cancer cell lines, curcumin reduces the activity and expression of COX-2, EGFR, and ERK1/2 in a dose-dependent manner, which results in the inhibition of cell survival and the promotion of apoptosis." (PMID 41515171, 2025). "We investigated 68 pancreatic cancer TMA specimens for membrane TF and EGFR expression by IHC and calculated H-scores." (PMID 39751657, 2025). "In pancreatic tumor tissues, AQP5 was correlated with EGFR, and AQP3 and AQP9 were correlated with c-Jun." (PMID 40305202, 2025).
pancreatic cancer (continued). "Rhein sensitizes human pancreatic cancer cells to EGFR inhibitors by inhibiting STAT3, providing an innovative framework for pancreatic cancer treatment, especially in combination with EGFR inhibitors." (PMID 40572668, 2025). "Both of these patients had KRAS testing as part of screening for potential inclusion in a trial of anti- Epidermal growth factor receptor (EGFR) monoclonal antibody, panitumumab, in KRAS wild-type pancreatic cancer." (PMID 41229506, 2025). "In this study, we found that pancreatic cancer cells expressing high levels of MAP17 showed increased sensitivity to some drugs, such as gemcitabine, 5-fluorouracil, cisplatin, or osimertinib, an EGFR inhibitor, in vitro." (PMID 40805270, 2025). "The top enriched pathways include AGE-RAGE, epidermal growth factor (EGFR), and VEGF, which are highly expressed in pancreatic cancer." (PMID 40573291, 2025). "DP9 effectively disrupts the interaction between EGFR and Gal-3, and suppresses the Gal-3/EGFR/AKT/FOXO3 signaling pathway, thereby exerting anti-pancreatic cancer activity." (PMID 41295391, 2025). "To further validate the correlations found, we analyzed publicly available datasets using TNMplot and observed significant correlations between AQP3 and c-Jun (p < 0.01), and AQP5 with EGFR (p = 0.040) and CDH1 (p < 0.01) in pancreatic cancer." (PMID 40305202, 2025). "In pancreatic cancer, PPY-induced iCAFs recruit M2 macrophages and suppress CD8+ T cell function via EGFR/NF-κB signaling." (PMID 41462979, 2025). "As a promising anti-pancreatic cancer drug candidate, DP9 demonstrates binding affinity to Gal-3 and inhibitory effects on the Gal-3/EGFR signaling pathway." (PMID 41295391, 2025). "Taken together, both EGFR and focal adhesion are two important players to be further investigated for their role in the CMG2-regulated cellular functions of pancreatic cancer cells, which can also shed light on their therapeutic potential." (PMID 39199664, 2024). "In gemcitabine‐resistant patient‐derived xenograft models of pancreatic cancer, acquired gemcitabine resistance was efficiently overcome by a pan‐HER antibody mixture, which was a cocktail of anti‐EGFR, anti‐HER2, and anti‐HER3 antibodies." (PMID 39651731, 2024). "In addition, L1CAM-integrin binding was shown to induce interleukin (IL)-1β production in pancreatic cancers, and IL-1β was reported to transactivate EGFR in OSCC, implying that the interaction of L1CAM and integrin might promote EGFR activation via inducing IL-1β upregulation in OSCC." (PMID 38263290, 2024). "Additionally, high glucose levels induce epidermal growth factor (EGF) expression and epidermal growth factor receptor (EGFR) transactivation, a well-known oncogenic pathway, in pancreatic cancer cell lines which may increase pancreatic cancer cell proliferation." (PMID 39410536, 2024). "The addition of the EGFR tyrosine kinase inhibitor (TKI), erlotinib, to gemcitabine chemotherapy for the first-line treatment of patients with advanced pancreatic cancer slightly improved outcomes." (PMID 38459558, 2024). "The first of these was the approval of erlotinib, an epidermal growth factor receptor (EGFR) inhibitor, in combination with gemcitabine for treatment of advanced pancreatic cancer." (PMID 39158669, 2024). "The activation of the IL-1β/epidermal growth factor receptor (EGFR)/extracellular-signal-regulated kinase (ERK) pathway is prompted by NETs, resulting in the promotion of migration, invasion, and EMT of pancreatic cancer cells." (PMID 38835055, 2024). "Both studies underscore a potential for EGFR- and HER2-directed T cell-based therapies in pancreatic cancer." (PMID 38650005, 2024). "In pancreatic cancer, EGF signaling triggered the EMT via integrin/EGFR/MAPK signaling, which induces decreases in E-cadherin and ZO-1." (PMID 38263290, 2024).
pancreatic cancer (continued). "The first-generation epidermal growth factor receptor (EGFR) inhibitor erlotinib is approved by the FDA for the treatment of non-small cell lung cancer (NSCLC) and pancreatic cancer." (PMID 39434878, 2024). "For example, MUC1 has been shown to act as a transcriptional inducer of ABCC1 in pancreatic cancer, whereas in cervical cancer, MUC1 promotes ABCB1 expression through an EGFR-dependent mechanism." (PMID 38254882, 2024). "In HCC and pancreatic cancer, LHPP binds to the epidermal growth factor receptor (EGFR) and inhibits its phosphorylation, negatively regulating the activation of downstream pathways, including ERK, AKT, and STAT3, leading to decreased metastatic potential." (PMID 39063217, 2024). "This receptor can suppress the EGFR/MAPK and PI3K/AKT signaling pathways in pancreatic cancer cells, thereby reducing the number and activity of cancer stem cells and also inhibiting the formation of liver metastases." (PMID 38567163, 2024). "In this path, ErbB1 (epidermal growth factor receptor/EGFR) and especially ErbB2 (HER2/neu) are more important in pancreatic cancer." (PMID 38559560, 2024). "In pancreatic cancer cells, NEU1 removes sialic acids from EGFR, leading to EGFR dimerization and the activation of pro-survival pathways." (PMID 39194692, 2024). "EGFR/ERBB2 was introduced in this study, and therapies targeting EGFR (such as erlotinib, an FDA-approved drug used for advanced pancreatic cancer) are among the most effective treatments for PDAC." (PMID 38982491, 2024). "In pancreatic cancer cells, TRPV1 exhibits a regulatory effect on the Epidermal Growth Factor Receptor (EGFR)." (PMID 38567163, 2024). "Curcumin suppressed the EGF/EGFR signaling pathway, which in turn prevented hyperglycemia-driven EGF-induced pancreatic cancer from migrating and invading by downregulating the ERK and Akt signaling molecules." (PMID 39770516, 2024). "Small molecules such as EGFR, HER248 and PI3K49 were studied extensively as potential targets for treating pancreatic cancer." (PMID 39730634, 2024). "Erlotinib, lapatinib, and icotinib bind to the EGFR in a reversible manner and have been approved as first-line therapies for advanced NSCLC and pancreatic cancer." (PMID 36768973, 2023). "By employing CRISPR/Cas9 gene‐editing technology we successfully deleted EGFR, ERBB2, ERBB3, and ERBB4, respectively, in the human pancreatic cancer cell line Panc‐1." (PMID 37341059, 2023). "Because HepG2 cells express low levels of EGFR26, we tested EGF-TAMRA binding to a human pancreatic cancer cell line, PANC-1, which expresses high levels of EGFR." (PMID 37061516, 2023). "We found that the combination of cetuximab (anti-EGFR mAb) and trastuzumab (anti-HER2 mAb) is efficient against pancreatic cancer, a disease with unmet medical needs and poor prognosis." (PMID 37153618, 2023). "PRMT5 induces the phosphorylation of the epidermal growth factor receptor (EGFR), upregulates the expression of β-catenin through the EGFR/AKT/β-catenin pathway, and promotes the EMT of pancreatic cancer cells to enhance tumor migration and invasion." (PMID 36902253, 2023). "As the authors report in vitro targeting efficacy tested against three pancreatic cancer cell lines (PANC-1, AsPC-1, and MIA Paca2) with variable epidermal growth factor receptor (EGFR) expression, and showed that gold uptake correlated with EGFR expression." (PMID 37711860, 2023). "This agent inhibits EGFR activity and EGFR-AKT-mTOR signaling, thereby inhibiting the proliferation of pancreatic cancer cells resistant to gemcitabine (MIA-GR100)." (PMID 38532833, 2023). "In this study, we investigated the expressions of EGFR, HER2, and VEGFR in GemHCl and 4NSG-SLN-treated PDX mouse models bearing pancreatic tumors." (PMID 37179357, 2023). "The local RAS system encourages tumor cell proliferation and angiogenesis by upregulating EGFR and VEGF expression and RAS inhibition induces apoptosis in pancreatic cancer cells." (PMID 38028629, 2023).
pancreatic cancer (continued). "For example, in pancreatic cancer, NETs promoted cell migration, invasion, and subsequent EMT activation via the EGFR/ERK pathway." (PMID 38201433, 2023). "When EGFR signaling is altered, it becomes the grand orchestrator of epithelial transformation and promotes EGF-induced EMT in pancreatic cancer." (PMID 36902253, 2023). "We have been developing 64Cu-labeled anti-epidermal growth factor receptor antibody NCAB001 (64Cu-NCAB001) for the early diagnosis and therapy of pancreatic cancer with positron-emission tomography." (PMID 37895812, 2023). "EGFR-induced phosphorylation of different pathways contributed to HIF-1α signaling loop, regulated glucose metabolism in pancreatic cancer, and promoted hepatocellular carcinoma progression." (PMID 36154925, 2023). "Previous studies have reported that potato carboxypeptidase inhibitors can inhibit the proliferation of pancreatic cancer by acting as a competitive inhibitor of epidermal growth factor (EGF) and by binding to EGFR." (PMID 36674593, 2023). "The humanized EGFR-targeting antibody LR004 showed anti-tumor activity when given as a single treatment in MIA PaCa-2 and PANC-1 pancreatic tumor models, with the response potentiated when multiple doses were given." (PMID 37880707, 2023). "The in vivo testing of these three highly efficient bispecific antibodies against EGFR and HER2 or HER3 in pre-clinical mouse models of pancreatic cancer showed deep antibody penetration in these dense tumors and robust tumor growth reduction." (PMID 37153618, 2023). "They administered lapatinib as a single agent in vivo for four types of pancreatic cancer cell lines (MiaPaca-2, PANC-1, Capan-1, and Capan-2) to identify HER2/EGFR expressions in each of the four pancreatic cancer cells." (PMID 36975494, 2023). "Erlotinib/ginsenoside Rg3 treatment increases the protein levels of caspase-3, caspase-9, and PARP while decreasing those of p-EGFR, p-PI3K, and p-Akt in pancreatic cancer cell lines and BALB/c nu/nu male mice by inhibiting the EGFR/PI3K/Akt signaling pathway." (PMID 37063281, 2023). "The impact of the 4NSG-SLN formulation was evaluated on EGFR, HER2, and VEGFR expressions in the mice's pancreatic tumor tissue." (PMID 37179357, 2023). "Among the BiXAbTM that most strongly inhibited the phosphoproteome in pancreatic cancer cells stimulated with the EGF+NRG1 ligand mix, anti-EGFR/HER3 BiXAbTM, including 3Patri-1Cetu-Fc and 3Patri-1Matu-Fc, were consistently more effective." (PMID 37153618, 2023). "Numerous studies had disclosed the relationship between MAPK signal pathway and EMT, such as Musashi2 promotes EMT in pancreatic cancer through ZEB1-ERK/MAPK, Integrin/EGFR-ERK/MAPK, and ERK/MAPK signaling pathway." (PMID 35898472, 2022). "DNAJB11 promoted cancer development through the EGFR/MAPK signaling pathway, providing new insight into the development of pancreatic cancer." (PMID 36209075, 2022). "In pancreatic cancer cells, overexpression of integrin β1 activates the FAK/tyrosine kinase/Akt pathway, resulting in EGFR-independent cell proliferation and, as a result, the ability to overcome EGFR suppression by cetuximab." (PMID 35205415, 2022). "TRPV1 can downregulate EGFR levels by inducing EGFR ubiquitination and degradation, thereby inhibiting the EGFR/MAPK signaling in pancreatic cancer cells." (PMID 36304985, 2022). "High-glucose culture of pancreatic cancer cell lines increases the expression of EGF, which then activates EGFR." (PMID 35222283, 2022). "Previous studies have shown co-expression of SPINK1 and EGFR in pancreatic tumors and SPINK1 promote pancreatic cancer cells through the mitogen-activated protein kinase (MAPK) pathway in vitro." (PMID 36053457, 2022). "In this study, periostin (POSTN) was discovered to increase LINC01133 via the epidermal growth factor receptor (EGFR)/MYC axis and promote exosome secretion in pancreatic cancer cells." (PMID 35055115, 2022).
pancreatic cancer (continued). "To establish the antibody panel for 64Cu-TuBA, we selected seven antigens (EGFR, HER2, HER3, TfR, EpCAM, LAT1, and CD98), which are reportedly overexpressed in pancreatic cancer patients." (PMID 35628616, 2022). "We analyzed mRNA expression levels of MYEOV, GPRC5A, KRAS, EGFR, SERPINB5, EIF4G2, and PDCD4 in pancreatic cancer tissues and normal tissues adjacent to pancreatic cancer from three pancreatic cancer patients." (PMID 36358856, 2022). "In this study, we evaluated the impact of the novel compound MFU on the expression of EGFR, HER2, and VEGFR in patient-derived pancreatic tumor tissues implanted in mice." (PMID 36550419, 2022). "ANO9 has been studied for its role in pancreatic cancer where, like ANO1, it binds to and activates EGFR and downstream ERK signalling." (PMID 36497413, 2022). "Kaempferol can enhance the sensitivity of pancreatic cancer cells to targeted drugs by inhibiting PI3K/AKT signaling pathway and epidermal growth factor receptor." (PMID 36147444, 2022). "Erlotinib, an oral EGFR-TKI, is currently widely used as an effective targeted therapy for patients with non-small cell lung cancer (NSCLC) and pancreatic cancer." (PMID 36165327, 2022). "We also validated the role of ceRNA network genes such as GPRC5A, SERPINB5, KRAS, EGFR, EIF4G2, and PDCD4 in pancreatic cancer." (PMID 36358856, 2022). "It was found that MYEOV, GPRC5A, SERPINB5, KRAS, EGFR, and EIF4G2 were all significantly elevated in pancreatic cancer tissues, and the expression trends of GPRC5A, SERPINB5, KRAS, EGFR, and EIF4G2 in different stages were nearly identical." (PMID 36358856, 2022). "Among them, EGFR and MAPK1 were significantly correlated with the survival of pancreatic cancer patients." (PMID 35449823, 2022). "To identify the correlation between the expression levels of TSPAN8, SOX9 and EGFR in PDAC, we performed IHC analysis of an additional cohort of 40 human pancreatic cancer specimens." (PMID 34163029, 2021). "In this preclinical study on pancreatic cancer cell lines, it proved equally effective in inducing tumor cell apoptosis, at even lower EC50 values than with erlotinib (EGFR inhibitor) or ibrutinib." (PMID 33445713, 2021). "In general, NETs promote pancreatic cancer EMT, migration and invasion dependent on EGFR/ERK pathway through IL‐1β, providing new thoughts on the interaction between NETs and pancreatic cancer cells." (PMID 33955688, 2021). "However, does EGFR mediated pancreatic cancer initiation was HSF1 dependent remains unclear." (PMID 33422093, 2021). "Upon EGF treatment, overexpression of miR-338-5p not only downregulated EGFR expression and inhibited MAPK/ERK signaling, but also inhibited EMT and metastasis process of pancreatic cancer (PC) cells." (PMID 33937024, 2021). "In conclusion, all the findings indicated that there was a correlation between EGFR and HSF1 in the tumorigenesis of pancreatic cancer." (PMID 33422093, 2021). "Initially, we investigated the role of two well characterized RTKs, EGFR and MET, in immune “hot” (CD8 + T-cell enriched) and “cold” (CD8 + T-cell decreased) pancreatic cancers." (PMID 34479614, 2021). "The epidermal growth factor receptor (EGFR) is a good target for PET imaging of early pancreatic cancer, as its overexpression is observed in about 90% of pancreatic cancer cases." (PMID 34681174, 2021). "In pancreatic cancer cell lines, SPINK1 was coprecipitated with EGFR in an immunoprecipitation experiment and trigger cancer cell proliferation via activating EGFR downstream signaling." (PMID 33916984, 2021).